ANXA2 (annexin A2)
Diseases named in the same sentence as ANXA2 in open-access papers (continued):
Sharing a sentence is not in itself a finding about the gene and the disease.
infection (continued). "To investigate whether cellular stress directly induces ANXA2 upregulation in TFCs, we treated thyroid follicular cell line Nthy with LPS or H2O2, as infection and stress are both risk factors for GD." (PMID 41126733, 2026). "As the infection progresses, the subsequent downregulation of ANXA2 might reflect a host response aimed at limiting parasite replication or a shift in the host cell's signaling pathways to promote apoptosis and limit further spread of the infection." (PMID 40777830, 2025). "During the early stages of infection, the upregulation of ANXA2 could facilitate parasite invasion by interacting with specific parasite proteins, as seen in other host-pathogen interactions." (PMID 40777830, 2025). "ANXA2 plays a role in the infection and replication processes of cells or viruses." (PMID 40487068, 2025). "Following ANXA2 knockdown, the cell apoptosis rate, caspase-3 activity, and Bax expression levels were significantly increased (P < 0.01), whereas the infection rate and Bcl-2 expression levels were significantly decreased (P < 0.01) compared to the group infected with E. tenella alone." (PMID 40777830, 2025). "We hypothesize that alterations in ANXA2 distribution during infection destabilize the ER and facilitate the acquisition of ER fragments that nucleate VFs." (PMID 41283634, 2025). "To evaluate a function for ANXA2 in reovirus replication, we infected wild-type (WT) and ANXA2-knockout (KO) HeLa cells with reovirus and assessed the progression of early and late stages of infection." (PMID 41283634, 2025). "In addition, numerous studies have shown that the overexpression of ANXA2 promotes infection by most pathogens, whereas the inhibition of ANXA2 using antibodies or siRNAs reduces infection by pathogens." (PMID 39057791, 2024). "In addition, ANXA2 can regulate immune responses, and in certain pathogen infections, it can interact with pathogen proteins to facilitate their invasion and proliferation." (PMID 39057791, 2024). "In contrast, the use of the S100A10 antibody in HaCaT cells inhibited infection in the late nucleus, suggesting that ANXA2 and S100A10 may have different roles." (PMID 39057791, 2024). "During pathogen infections, ANXA2 modulates the nuclear factor kappa-B (NF-κB) and cell apoptosis signaling pathways and guides the chemotaxis of inflammatory cells toward inflammation sites, thereby protecting the host organism through the modulation of the inflammatory response." (PMID 39057791, 2024). "Further studies demonstrated that the shRNA-mediated suppression of AnxA2 resulted in an impairment in SCV perinuclear positioning, suggesting that AnxA2 may contribute to this infection phenotype." (PMID 38673776, 2024). "In addition, ANXA2 regulates inflammatory responses and plays an important role in the infection process of bacteria, viruses, and other pathogens." (PMID 39057791, 2024). "A proteomic screen revealed that annexin A2 (AnxA2) interacts with SopD2 during infection." (PMID 37279149, 2023). "ANXA2 also engages with M. hyorhinis p37, activating the NF-κB pathway to mediate infection." (PMID 37978536, 2023). "The precise mechanism by which Annexin A2 facilitates nidovirus replication and infection remains unclear, and the specific interactions between Annexin A2 and nidovirus proteins warrant further investigation." (PMID 37482693, 2023). "Taken together, we speculated that the intrauterine transmission of HBV might utilize a similar vesicle transport mechanism to achieve maternal and infant infections through S100A10/AnxA2-mediated exocytosis in placental cells." (PMID 34645932, 2022). "In addition, ANXA2 expression promoted a permissive environment for infection, induced suppression of immune activation and reduced the Th-1 cytokine production in vitro." (PMID 36159852, 2022).
infection (continued). "tBHQ upregulated mRNA expression of many receptors that are involved in virus entry, such as Anxa2 and FPR-RS2 (Anxa1) receptors (they bind virus associated Anxa proteins that promote infection of the host cell) and other “minor” receptors, e.g., Cd14 and Mgl1." (PMID 35629310, 2022). "Reducing annexin A2 increased apoptosis in the infection of EMCV." (PMID 35215950, 2022). "Similarly, the protein band density significantly increased with infection time, indicating that M. bovis infection promotes the expression of ANXA2 gene in EBL cells." (PMID 36159852, 2022). "Early infection with dengue virus serotype 2 (DENV2) produces an increase in the synthesis of AnxA2, a protein involved in cytoskeletal rearrangements that could also serve as a host cell factor for viral internalization." (PMID 34681689, 2021). "Using this technique, we demonstrate that SopD2 and PipB2 both bind to AnxA2 which may play a role in SCV intracellular positioning during infection." (PMID 34880286, 2021). "WT (n = 14) and ANXA2-KO (n = 15) mice were inoculated with an ordinarily lethal dose of R. australis (2 x 106) via tail vein injection (i.v.) and observed up to 10 days post-infection (p.i.)." (PMID 32687500, 2020). "Overall, our study revealed a novel role of ANXA2 in the formation of CMHs during R. australis and Ebola virus infections; and the underlying mechanism is relevant to the role of ANXA2-regulated tight junctions and its role in stabilizing the BBB in these deadly infections." (PMID 32687500, 2020). "In early infection, according to our working model, AnxA2 may support infection by acting as an anchor protein that promotes adhesion and internalization of bacteria and viruses, regulating actin dynamics at adhesion sites, and enabling virus assembly." (PMID 32575495, 2020). "Interestingly, cadherin complex protein cadherin 2 and talin 1 were upregulated in ANXA2-KO after infections." (PMID 32687500, 2020). "On the other hand, there is evidence that cell surface annexin AnxA2 may be co-opted to facilitate infection by invading bacteria such as Pseudomonas aeruginosa, Escherichia coli, Salmonella typhimurium, and Rickettsial species." (PMID 32575495, 2020). "In this instance, AnxA2 enables the initiation of productive infection." (PMID 32575495, 2020). "The functional interaction between ANXA2 and hsp90 in the context of pathogen infection is largely unknown." (PMID 32687500, 2020). "However, when S100A10 alone is knocked-out, only a moderate reduction in infection is observed, emphasizing the importance of delineating the roles of monomeric AnxA2 versus heterotetrameric A2t." (PMID 30568638, 2018). "AnxA2 also has immunomodulatory effects, and it therefore possible that AnxA2 expression promotes a permissive environment for infection through modulation of innate immune responses." (PMID 30568638, 2018). "Knockdown of AnxA2 via shRNA in cervical epithelial cells (HeLa) caused reduced MV progeny virus generation 24 h post-infection, but did not affect MV entry and RNA replication." (PMID 30568638, 2018). "Additionally, the slight differences in the viral expression at early stages between the siRNA treatment groups and control groups also suggested that ANXA2 promoted viral replication in ways other than activating infection." (PMID 28893180, 2017). "Our previous work showed that Mycoplasma hyorhinis (M. hyorhinis) infection was mediated by the interaction between p37 of M. hyorhinis and Annexin A2 (ANXA2) of host cells, however the translational value of this mechanism was unknown." (PMID 26812398, 2016). "Importantly, the data suggests that ubiquitin, annexin A1, annexin A2, MavP are putative novel interaction partners and that Rab1A, Rab1B, Rab6, and Rab10 are the predominant Rab GTPases targeted by SidM during infection." (PMID 26755725, 2016).
infection (continued). "Finally, the restoration of damaged tissues during the initial immune response by angiogenesis, for example, was induced as early as 4 days post infection as documented by an increased expression of angiogenin, annexin a2, fibronectin and ferritin heavy chain." (PMID 23094107, 2012). "Duck beta-actin and annexin A2 expression were detected down-regulated in the DHBV-infected PDHs at 12-120 h post-infection with mouse anti-beta-actin and anti-duck-annexin A2 as primary antibodies, that were consistent with the protein expression pattern revealed by the 2-DE analysis." (PMID 20529248, 2010). "To determine whether ANXA2 regulates the formation of VFs early in infection, we quantified cells containing VFs in WT and KO cells at 7, 8, 9, and 10 h post-adsorption in a synchronized infection in which cells were incubated for 30 min on ice during adsorption." (PMID 41283634, 2025). "Furthermore, ANXA2 expression in the control group increased slightly after infection." (PMID 28893180, 2017). "ANXA2 is involved in filopodia formation, required for a successful DENV infection, and its knockdown reduces DENV-2 viral production and infection." (PMID 39976655, 2025). "Taken together, our observations suggest that As blocked the AnxA2 MAC-T cells receptor and prevents its interaction with and combined with the bacterial ClfB receptor resulting decreased infection levels." (PMID 38414081, 2024). "Taken together, these results indicate that SARS-CoV-2 infection effectively downregulated de novo transcription of both ANXA2 and S100A10 early during infection." (PMID 38913740, 2024). "This work provides better insight into cell-surface AnxA2 and ADGRL2, which upregulate Src and p38MAPK signaling pathways to enhance ARV entry and productive infection." (PMID 37097149, 2023). "Overall, this review provides the molecular insights into a potential role of AnxA2 in the SARS-CoV-2 pathogenesis and post-infection complications, especially thrombosis, cytokine storm, and insulin resistance." (PMID 34681689, 2021). "Dziduszko and Ozbun also showed that both ANXA2 and S100A10 play a role in HPV16 entry and infection by showing that early HPV16 binding results in the translocation of AIIt to the extracellular surface." (PMID 34944495, 2021). "We previously showed that the exchange protein directly activated by cAMP (EPAC) plays a critical role during SFGR infections and that EPAC regulates ANXA2-mediated vascular fibrinolysis." (PMID 32687500, 2020). "Additionally, AnxA2 may play a role in initiating adaptive immune responses against infections." (PMID 30568638, 2018). "To explore the initiation of infection-related MDR, we employed A2PP to block the P37 protein from binding ANXA2." (PMID 28976984, 2017). "CLSM microscopy also demonstrated greatly increased endosomal compartments, with concomitant recruitment of AnxA2 and TRAM in macrophages after Kp-GFP infection." (PMID 26527544, 2015). "In the absence of ANXA2, the actin cytoskeleton and ER are dismantled prior to infection, allowing for rapid recruitment of ER fragments to VFs and accelerated reovirus factory formation." (PMID 41283634, 2025). "Conversely, in non-smokers with significantly higher AnxA2 levels, HPV can bind more easily to unoccupied – non-SLPI-bound – AnxA2, making successful infection of the cells more likely." (PMID 40655928, 2025). "In the absence of ANXA2, ER fragments are available at the initiation of infection and, therefore, VFs can form more rapidly in the presence of unchanged levels of nonstructural proteins." (PMID 41283634, 2025). "In the absence of ANXA2, the actin cytoskeleton and ER network are disrupted, and reovirus factory formation and infection progress more rapidly than in cells expressing ANXA2." (PMID 41283634, 2025). "Instead, Annexin A2 can directly interact with influenza viruses to mediate infection without using the fibrinolytic conversion mechanism." (PMID 37482693, 2023).
infection (continued). "Additionally, the virulence protein 2A of EMCV interacts with Annexin A2 via the activation of the JNK/c-Jun pathway, which inhibits apoptosis and promotes EMCV replication during the early stage of infection." (PMID 37482693, 2023). "Conversely, in non-smokers with significantly higher levels of AnxA2 compared to SLPI, HPV can bind more readily to unoccupied—non-SLPI-bound—AnxA2, and successful infection of cells is likely." (PMID 34207440, 2021). "To ensure that the observed inhibition of infection was specifically due to the S100A10 and AnxA2 gene editing, we restored AnxA2 expression in the A2t KO cells by plasmid transfection which stabilized S100A10 protein expression and thus reintroduced heterotetrameric A2t." (PMID 30076379, 2018). "The differences between infection in S100A10 KO versus A2t KO cells could be explained by the fact that S100 family members S100A4, S100A6, and S100A11 are also able to complex with AnxA2 and are expressed in cervical epithelium." (PMID 30076379, 2018). "It has also been demonstrated that ANXA2 can facilitate the conversion of plasminogen (PLG) into plasmin, providing the protease activity necessary for the cleavage of precursor HA molecules to activate infection." (PMID 28893180, 2017). "However, treating cells with anti-PSGL-1, anti-SCARB2, and anti-ANXA2 monoclonal antibodies or lectins did not entirely block the infection in EV-A71 host cells." (PMID 40377310, 2025). "To determine whether levels of μNS, which is expressed early in infection, are altered in the absence of ANXA2, we quantified μNS levels in reovirus-infected WT and KO cells using immunoblotting." (PMID 41283634, 2025). "More importantly, Co-IP assays using IgG and ANXA2 rabbit monoclonal antibody (MAb) suggested that US3 and Src could be detected in wild-type PRV-infected cells, whereas only Src was detected in the ΔUS3-type infection condition." (PMID 36786600, 2023). "First, we demonstrated that ANXA2 mRNA and protein levels increased during the invasion of M. bovis, and S100A10, the interacting protein of ANXA2, was also upregulated in M. bovis infection, indicating ANXA2 might together with S100A10 participate in its infection." (PMID 36159852, 2022). "The number of invaded M. bovis in siANXA2-1 transfected EBL cells was significantly (p < 0.0001) reduced as compared to siCtrl transfected EBL cells (control) irrespective of infection time point indicating that ANXA2 plays a significant role in the invasion of M. bovis into EBL cells." (PMID 36159852, 2022). "This study is the first to show that ANXA2 plays a role in promoting the replication of H5N1 AIV strains through a unique mechanism that does not require the conversion of PLG into plasmin to initiate infection." (PMID 28893180, 2017). "Following infection of WT cells, we observed the characteristic ER remodeling induced by reovirus, in which the ER becomes thin and fragmented (50% increase) and forms small collapsed structures (39% increase), similar to the ER morphology of mock-infected cells in the absence of ANXA2." (PMID 41283634, 2025). "However, PLG interacted with NCL, not ANXA2, during EV-A71 infection." (PMID 40377310, 2025). "Notably, several members from Annexin A family (ANXA1, ANXA2, ANXA4, ANXA5 and ANXA6) were overrepresented in DEVs from Lm-infected BMDCs but remained unaltered in total cell lysates, suggesting a specific sorting during infection of these ANXA family members to EVs." (PMID 36131943, 2022). "Overall, the observed reduction in infection is less significant in the absence of S100A10 alone compared to full A2t, supporting an independent role for monomeric AnxA2." (PMID 30076379, 2018). "By comparing the fluorescence intensity and Western blot, we found that the expression of AnxA2 and the amount of intracellular virus was not significantly related to the duration length of infection, indicating that the rate of HBV exocytosis does not depend upon the time of infection." (PMID 34645932, 2022).
bacterial infection (9 papers, 2014 to 2024). "Conversely, previous studies suggest that Anxa2 deficiency increases pro-inflammatory response after bacterial infection in the lung." (PMID 38253182, 2024). "Interestingly, a previous study demonstrated that AnxA2 deficiency led to an intensified pro-inflammatory response associated with an increased oxidative burst and inflammatory response after bacterial infection in the lung." (PMID 31817350, 2019). "The S. aureus surface located fibrinogen-binding protein (clumping factor; ClfB) and the cell membrane binding protein Annexin A2 (AnxA2) structurally interact to facilitate bacterial infection of MAC-T cells." (PMID 38414081, 2024). "This suggests that ANXA2 protects the host from damage due to excessive inflammatory response during bacterial infection." (PMID 39057791, 2024). "Annexin A2 promotes the formation of phagophores, an essential step in the process of autophagy thus contributing to host immunity during bacterial infection." (PMID 35086476, 2022). "Here we have found that AnxA2 expression is a key step in negative regulation of inflammatory responses to bacterial infections, acting as a molecule to induce internalization of TLR4, followed by recruitment to early endosomal membranes." (PMID 26527544, 2015). "Furthermore, ANXA2 regulates the inflammatory response in bacterial infections and autophagy through the Akt1-mTOR-ULK1/2 signaling pathway during Pseudomonas aeruginosa infections, which promotes host immunity against bacteria." (PMID 39057791, 2024).
cardiovascular diseases (6 papers, 2012 to 2025). "FOXO3 and YWHAB are linked to neurodevelopmental disease, while FOXO3 and ANXA2 are associated with cardiovascular diseases." (PMID 38184718, 2024). "ANXA2 is also implicated in the cardiovascular diseases related to ESRD." (PMID 36120574, 2022). "Additionally, annexins included in the pathways upregulated in iVSMCs have been linked to cardiovascular disease and identified as having therapeutic potential (ANXA1, ANXA2)." (PMID 39796045, 2024). "ANXA2 is also involved in the pathogenesis of cardiovascular diseases." (PMID 34109194, 2021). "Second, the interaction between S100A10 and ANXA2 may involve other complex molecular mechanisms that require further exploration and the clinical application of S100A10 and ANXA2 in cardiovascular diseases requires evaluation through larger-scale clinical studies." (PMID 41195005, 2025).